TBK1 (TANK binding kinase 1)
Diseases named in the same sentence as TBK1 in open-access papers (continued):
Sharing a sentence is not in itself a finding about the gene and the disease.
tumor (continued). "To understand the potential relevance of this finding, we next examined expression of STING and activation of its immediate downstream target, phosphorylated TBK1 (pTBK1), across different tumor microenvironments in tissue microarrays (TMA) of patient samples." (PMID 33013881, 2020). "Increasing evidence has revealed that both TBK1 and IKKε participate in signaling pathways that impact cell transformation and tumor progression." (PMID 30791439, 2019). "This group argues that the effect of TBK1/IKKε is at the level of T cells, where IL-2 and IFNγ are increased with inhibition, and at the tumor cell level where TBK1/IKKε inhibition leads to decreased C-C motif chemokine ligand 5 (CCL5) and IL-6." (PMID 30223576, 2018). "The binding of tumor cells to bone marrow osteoblasts induces TANK binding kinase 1 (TBK1) expression that leads to inhibition of mTOR signaling and cell cycle arrest." (PMID 30180883, 2018). "Barbie and colleagues used organotypic tumor spheroids (which retain lymphoid and myeloid components) to implicate both TBK1 and IKKε in promoting resistance to anti-PD-1 therapy." (PMID 30223576, 2018). "Recently, it has been shown that chemical inhibition of TBK1/IKKε dimer activity significantly impairs tumor development in xenograft models." (PMID 27577074, 2017). "TBK1 has been shown to be necessary for the survival of mutant K-Ras-expressing tumour cells, where TBK1 signalling induces c-Rel and BCL-XL10 and activates Akt7." (PMID 26656453, 2015). "cGAS-STING-TANK-binding kinase 1-interferon regulatory factor 3 (TBK1-IRF3) signaling pathway leads to immune cell-mediated tumor suppression by recognizing DNA released into the cytoplasm during chromosomal instability thereby regulating gene expression and inducing apoptosis." (PMID 40191727, 2025). "Studies have shown that TBK1 inhibition not only suppresses cancer progression by directly inhibiting cancer cell proliferation and survival but also suppresses cancer development by activating anti-tumor T cell immunity." (PMID 40822284, 2025). "Upon release inside the tumor microenvironment, these payloads activate the STING pathway in tumor and immune cells, triggering a signaling cascade that culminates in the phosphorylation of TBK1 and IRF3, resulting in robust type I interferon production and pro-inflammatory cytokine secretion." (PMID 40872592, 2025). "This may provide mechanistic insights into TBK1’s ability to modulate the tumor microenvironment and cancer immunology." (PMID 40412527, 2025). "Results proved that STING, phosphorylated STING (pSTING), phosphorylated TANK-binding kinase 1 (pTBK1), and phosphorylated interferon regulatory factor 3 (pIRF3) are up-regulated in tumor tissues after 131I-Mn/SAE@M treatments, confirming the activation of the STING signaling pathway." (PMID 40968370, 2025). "In addition, knockdown or inhibition of TBK1 and IKKε reduced tumor sphere growth, which is supported by loss of stemness signaling signatures with ERK inhibition and with TBK1–IKKε inhibition." (PMID 40738190, 2025). "Interestingly, one of the tumor-adjacent samples exhibited elevated expression of TBK1 and phosphorylated TBK1 (P-TBK1), and this correlated with a modest elevation of P-ERK." (PMID 40738190, 2025). "TBK1 mediates immunosuppression by promoting tumor inflammation, thereby promoting tumor growth." (PMID 40076567, 2025). "Furthermore, this study discovered that TBK1 mediates tumor T cell depletion and glycolysis, thereby contributing to immunosuppression." (PMID 39161768, 2024). "Thus, the TBK1-IFN pathway not only promotes anti-tumor immune surveillance but also mediates tumor development through sustained inflammatory stimulation." (PMID 39161768, 2024). "Similarly, the coimmunoprecipitation of both STING and TBK1 with IRF3 was improved in R‐MCF7 cells when tumor cells were treated with MK2206." (PMID 39023171, 2024).
tumor (continued). "In conclusion, these results suggest that POLE mutations may impede tumor growth and trigger anticancer immune responses through the STING/TBK1/IRF3 signaling pathway." (PMID 38238314, 2024). "However, IKBKE exhibited lower methylation levels in tumor samples, whereas TBK1 showed higher methylation levels in tumor samples compared to normal samples." (PMID 38817870, 2024). "Hence, comprehending the role and mechanism of TBK1 in diverse tumor backgrounds holds significant value in maximizing the efficacy of TBK1 inhibitors." (PMID 39161768, 2024). "Moreover, even in most tumors, TBK1 still has the tag of immune escape genes, but it is undeniable that it still has the effect of activating innate immunity at the early stage of tumor development, and its importance cannot be ignored." (PMID 39161768, 2024). "In addition to directly regulate cancer cell proliferation and survival, TBK1 plays a significant role in promoting tumorigenesis by altering the function of immune cells within the tumor microenvironment." (PMID 39279883, 2024). "The study of TBK1's function in immune cells within tumor microenvironment has been emerging." (PMID 39279883, 2024). "Activation of the TBK1-IFN pathway may also offer an opportunity for clearing resistant residual tumor cells through immunotherapy." (PMID 39161768, 2024). "Notably, in promoting tumor PD-L1 expression, TBK1 and IFN mutually extend and complement each other." (PMID 39161768, 2024). "TBK1, which is expressed in almost all tissues, has complex upstream signals related to its activation and mediates downstream pathways that span multiple stages of tumor development." (PMID 39161768, 2024). "For a comprehensive review of TBK1's role in tumor immunity, please see." (PMID 39279883, 2024). "Special attention should be given to the modulation of the tumor microenvironment by TBK1-IFN, as targeting or activating this pathway may offer strategies to enhance the efficacy of immunotherapy." (PMID 39161768, 2024). "Furthermore, the combination therapy significant enhanced the phosphorylation of TBK1 in EpCam+ tumor cells." (PMID 39023171, 2024). "Additionally, the POLE P286R mutant also increases cGAS level, promotes TBK1 phosphorylation, and stimulates inflammatory gene expression and anti-tumor immune response." (PMID 38238314, 2024). "Moreover, the interplay between TBK1 and the inflammatory process within the tumor microenvironment further highlights its significance in cancer biology." (PMID 38567349, 2024). "Therefore, focusing on the downstream common TBK1-IFN pathway of multiple signaling pathways is crucial for promoting the efficacy of tumor PD-L1 checkpoint inhibitors." (PMID 39161768, 2024). "Previously, TBK1 garnered widespread attention owing to its immune and anti-tumor effects." (PMID 39030571, 2024). "Furthermore, double immunofluorescence staining showed that the phosphorylation of TBK1 in EpCam+ tumor cells in the combined treatment group was much higher than that in the control group and the monotherapy group." (PMID 39023171, 2024). "As important proteins in innate immunity, STING and TBK1 play important roles in tumor progression." (PMID 39061024, 2024). "The correlation between TBK1 and tumour size, lymph node metastasis, or TNM stage suggested that TBK1 may be involved in tumour progression in CCA." (PMID 36928362, 2023). "Researchers also demonstrated using a patient-derived organotypic tumor spheroids (PDOTS) and a matched PDO drug screening platform that inhibition of innate immune kinase TANK-binding kinase 1 coupled with PD-1 blockade was an effective strategy for overcoming tumor immunotherapy resistance." (PMID 37081982, 2023).
tumor (continued). "Knockdown of TBK1 abrogated the tumour-promoting effect and inhibited CCA progression." (PMID 36928362, 2023). "It has been proposed that AXL inhibition can be achieved by blocking TBK1 (TANK binding kinase 1)/NF-κB pathway, a key signal pathway of immune cells, changes the composition of chemokines and cytokines in tumor microenvironment, making tumor sensitive to treatment." (PMID 37328828, 2023). "The xenograft tumor assay showed that TBK1 short hairpinRNA inhibited tumor growth." (PMID 36988258, 2023). "Existing studies have shown that TBK1 small molecule inhibitors have certain anti-tumor activity." (PMID 35747750, 2022). "These factors stimulate tumor angiogenesis by promoting the proliferation of endothelial cells, suggesting that TBK1 may function as an angiogenic effector." (PMID 35395857, 2022). "Three URs (ARHGAP21, KLF4, TBK1), among those that discriminated responding and non responding patients in the baseline tumor samples, lost significance in subsequent biopsies, possible reflecting the shift in the transcriptomic programs of the neoplastic lesions occurring as result of therapy." (PMID 36397155, 2022). "Interestingly, the genetic inhibition of Tbk1 in DCs enhances antitumor immunity and arrests tumor development." (PMID 35395857, 2022). "A previous study reported that TBK1 resulted in tumor immunosuppression and may be therapeutically beneficial to patients, in an effort to augment tumoral T-cell infiltration." (PMID 33679751, 2021). "Confirming TBK1 vs. IKKα/β dichotomy of mRIPO vs. LPS treatment, tumor homogenate cytokine analysis revealed stronger IKKα/β-driven cytokine induction by LPS (IL-6, TNF, IL-1β, IL-10), with CXCL10 (TBK1-dependent) being the most prominently induced cytokine after mRIPO treatment." (PMID 33767151, 2021). "Moreover, TBK1 contributed to tumor immunosuppression by down-regulating the expression of co-stimulatory molecules and decreasing T cell-priming activity in dendritic cells." (PMID 33679751, 2021). "However, another study yielded contrary results indicating that TBK1 participated in the activation of stimulator of the interferon genes pathway, enhancing antitumor immunity in the tumor microenvironment." (PMID 33679751, 2021). "However, more investigations on the role of TBK1 in immune-competent animals with tumor are warranted." (PMID 33679751, 2021). "In addition, the TBK1 antagonist resulted in the decreased level of α-SMA+ myofibroblasts in non-tumor liver tissues and IL-6 in tumor tissues demonstrated by IHC staining and ELISA." (PMID 33679751, 2021). "Another factor that proved to be important in tumour dormancy is tank-binding kinase 1 (TBK1)." (PMID 32527062, 2020). "Increasing evidence indicates that TBK1 could regulate the NF-κB signals, which is associated with EGFR-associated drug resistance acquisition in tumor cells." (PMID 31316001, 2019). "TBK1 inhibition plus lapatanib (an EGFR family inhibitor) strongly blocked xenograft tumor growth." (PMID 30223576, 2018). "Our finding that TBK1 functions are necessary for mitosis suggests that the dependency of mutant K-Ras tumour cells on TBK1 for cellular transformation also reflects its roles in directing progression through mitosis, by targeting PLK1 as well as other targets like CEP170 and NuMA." (PMID 26656453, 2015). "We speculate that TBK1-catalyzed phosphorylation of syntenin-1 could alter its functional capacity in exosome secretion, thereby modulating intercellular communication among tumor cells and immune cells within the tumor microenvironment." (PMID 40412527, 2025). "However, targeting TBK1 in tumor cell lines harboring KRAS mutations failed to significantly impede tumor growth." (PMID 39161768, 2024). "However, it is unclear whether MARCH1 regulates tumor progression by targeting the TBK1-mTOR signaling pathway." (PMID 39061024, 2024).
tumor (continued). "Hence, the paradoxical role of TBK1 in tumor development may necessitate acknowledgment in light of its downstream IFN-I signaling cascade." (PMID 39161768, 2024). "Therefore, this review synthesized the signaling pathways and physiological effects mediated by TBK1 in different tumor backgrounds to visually demonstrate the duplex nature of TBK1 in tumor development, in order to provide a reference for the rational application of TBK1 inhibitors in tumors." (PMID 39161768, 2024). "Interestingly, TBK1-loss did not slow down tumour growth in immunodeficient mice; however, targeting TBK1 pharmacologically promoted a more immunostimulatory effect in the TME because it increased the infiltration of CD8 T cells and M1 macrophage into tumours." (PMID 37503572, 2023). "Moreover, Cho-TBK1-HDO significantly reduced the number of orthotopic xenograft tumours." (PMID 36928362, 2023). "However, TBK1 is downregulated in uterine corpus endometrial carcinoma and oligodendroglioma, where it may function as a tumor suppressor." (PMID 35395857, 2022). "In addition to HCC, TBK1 may also regulate the resistance of other malignant tumor cells to antitumor drugs." (PMID 35747750, 2022). "Therefore, we further verified and analyzed the interaction between circLIFR and TBK1 and determined whether this interaction mediates the tumor-promoting effect of circLIFR." (PMID 36176304, 2022). "Therefore, the up-regulated TBK1 expression, which is predictive of poor prognosis, may contribute to tumor progression especially in BRCA, KIRC, and LIHC." (PMID 33679751, 2021). "The landscape of tumor-infiltrating immune cells was obtained using the CIBERSORT algorithm, and 22 types of immune cell profiles in patients from the HCC data set of TCGA were constructed to further confirm the association of TBK1 expression with the immune effector cells in this disease." (PMID 33679751, 2021). "The substantial deficiencies in tumor growth and progression that were induced by the FIP200 KI allele without significant activation of TBK1-IFN signaling led us to the interpretation that FIP200's non-canonical-autophagy function was responsible for limiting heightened anti-tumor immune responses." (PMID 32743346, 2020). "Besides promoting tumor growth, TBK1 was also involved in tumor-mediated immunosuppression." (PMID 33006365, 2020). "Activation of STING in γδ T cells increases the mRNA levels of TBK1, Eomes, and IFN‐Υ, exerting anti‐tumor effects in a STING‐dependent manner." (PMID 39573933, 2025). "Following this activation, TANK-binding kinase 1 (TBK1) and IRF3 are phosphorylated, leading to type I IFNs and inflammatory agents, all of which contribute to the tumor immune response." (PMID 41157253, 2025). "Inhibiting TBK1/IKKε correlated with reduced RIPK1 S25 phosphorylation, shifted TNF signaling toward cell death, and sensitized tumor cells to CD8+ T cell attacks." (PMID 41315176, 2025). "Subsequently, we detected the phosphorylation levels of TANK‐binding kinase 1 (TBK‐1) and interferon regulate factor 3 (IRF‐3) in CT26, H22, and GL261 cells using phosflow, and the IFN‐β level in tumor cell supernatants and tumor tissues homogenates by ELISA." (PMID 40470716, 2025). "DS specifically binds to LRP1, disrupts lysosomal function, and activates TBK1-dependent IFN-I signaling, thereby reprogramming the TME and enhancing the tumor’s response to anti-PD-1 or STING agonist treatment." (PMID 40625660, 2025). "By disrupting TBK1/IKKε recruitment to the TNFR1 complex, the balance can be shifted from survival to death, overcoming tumor resistance." (PMID 41315176, 2025). "c-di-GMP inhibits 4T1 cell growth and increases phosphorylation of STING, TBK1, IRF3 and STAT1 and the IFN-β level in tumor-bearing mice." (PMID 40552295, 2025). "This conclusion is supported by recent evidence demonstrating that TBK1 promotes intratumoral CD8+T cell infiltration and enhances tumor sensitivity to ICB therapy." (PMID 40625660, 2025).
tumor (continued). "In this context, our in vivo experiments have demonstrated that targeting the CMA translocase enzyme LAMP2A inhibits the degradation of STING and TBK1, enhancing the infiltration of IFNγ+CD8+ T cells and thus improving the "cold" tumor state." (PMID 40083918, 2025). "IF and IHC experiments demonstrated a significant increase in the expression of phosphorylated TBK1 (p-TBK1), phosphorylated IRF3 (p-IRF3) and IFN-β within the tumor tissue after combination therapy." (PMID 40355720, 2025). "Our results indicate that genetic ablation of Daxx up-regulated the p-TBK1 and p-IRF3 expression levels to sensitize chemotherapy, suggesting that Daxx is a negative regulator of the STING signal, thereby slowing tumor growth in vivo." (PMID 40296918, 2025). "This recognition triggers a cascade of phosphorylation events involving STING, TBK1, and IRF3, ultimately leading to the secretion of type I interferons, which induce an anti-tumor immune response." (PMID 40761260, 2025). "Specifically, MYOC, TBK1, COL1A1, and COL1A2 were upregulated in tumor tissues, while FOXC1, LRP2, and TEK was downregulated (all p < 0.05)." (PMID 40808675, 2025). "Based on this, we further found that the TBK1-IFN pathway, which is generally believed to mediate the anti-tumor effect of innate immunity, also has a pro-tumor effect." (PMID 39161768, 2024). "Meanwhile, the phosphorylation of STING, TBK1, and IRF3 activity were both abolished when using mtDNA-depletion versus control tumor mouse CRC cells." (PMID 38853246, 2024). "Activation of the TBK1-IFN pathway by MEDI2228 enhances CD38 expression in multiple myeloma cells, thereby augmenting the anti-tumor effects of CD38-targeting antibody-drug conjugates." (PMID 39161768, 2024). "Initially, we examined the expression levels of key genes within the innate immune pathway, namely DDX58, MAVS, C6orf150, TMEM173, IKBKE, TBK1 and IRF3, across diverse tumor and non-tumor tissues." (PMID 38817870, 2024). "Kaposi’s sarcoma-associated herpesvirus, associated with various tumor incidences, inhibits the interaction between STING and TBK1 through vIRF1, thereby blocking IFN-β generation and promoting tumor occurrence and viral spread within the population." (PMID 39161768, 2024). "Overall, the TBK1-IFN pathway enhances immune cell activation and tumor cell apoptosis, thereby boosting tumor immune response." (PMID 39161768, 2024). "Alterations in the expression of DDX58, MAVS, C6orf150, TMEM173, IKBKE, TBK1 and IRF3 were analyzed across different tumor samples using cBioPortal." (PMID 38817870, 2024). "Through the detection of proteins related to STING pathway in clinical tumor samples of CRC patients, we found that the levels of cGAS, STING, TBK1, IRF3 proteins and phosphorylation in CRC tissues all decreased." (PMID 39054486, 2024). "Common clinical treatments such as chemoradiotherapy can stimulate the TBK1-IFN pathway to inhibit tumor growth, but it is also necessary to avoid inhibiting the TBK1-IFN pathway that plays an anti-tumor role, such as sorafenib." (PMID 39161768, 2024). "For example, the AhR-target PARP7 (product of the gene TIPARP), can directly suppress STING activity by facilitating the degradation of TBK1, a key downstream effector kinase of STING, thereby suppressing IFN-I expression and subsequent anti-tumor immunity." (PMID 38459088, 2024). "It has been observed that TBK1 is upregulated in various tumors, with its expression inversely correlated with immune cells other than CD4 T cells in the tumor microenvironment." (PMID 39161768, 2024).